SNORD38A (small nucleolar RNA, C/D box 38A)
Synonyms: U38A; RNU38A
Gene: Small nucleolar RNA gene on chromosome 1 (44,777,843 to 44,777,912, forward strand). Ensembl gene ENSG00000202031.
Gene Ontology:
Biological process: RNA processing
Cellular component: nucleolus
Homologues: Orthologues: chimpanzee SNORD38A (100% identical), macaque SNORD38A (94% identical), pig SNORD38A (89% identical), rabbit SNORD38A (87% identical), mouse Snord38a (79% identical), rat Snord38a (79% identical). Paralogues in human: SNORD38B (71% identical), SNORD38C (67% identical), SNORD38D (67% identical).